CD24 (CD24 molecule)
Diseases named in the same sentence as CD24 in open-access papers (continued):
Sharing a sentence is not in itself a finding about the gene and the disease.
tumor (continued). "CD24 expression on the surface of tumor cells interacts with Siglec-10, which is expressed on immune cells, promoting tumor immune escape through corresponding molecular mechanisms in vitro among T and B lymphocytes, macrophages and NK cells." (PMID 38138858, 2023). "Since CD24 is highly expressed in various tumor cells, it is related to the invasion and progression of tumor cells." (PMID 37359556, 2023). "Nevertheless, the exact mechanisms through which CD24 contributes to drug resistance in tumor cells remain incompletely elucidated, involving a complex interplay of diverse pathways." (PMID 38313430, 2023). "Another “don’t eat me” signal, the recently discovered CD24/Siglec-10 axis facilitates macrophage infiltration into the tumor by Siglec-10-mediated sensing of CD24 and is complementary to CD47 signaling." (PMID 37822933, 2023). "The CD24 expression on tumor cells in the treatment group mice was significantly downregulated, and tumor growth was inhibited." (PMID 37846296, 2023). "SWA11, another anti-CD24 mAb, enhanced the anti-tumor effects of doxorubicin, oxaliplatin, 5-fluorouracil, irinotecan and paclitaxel, among other chemotherapy agents." (PMID 37846296, 2023). "Some malignancies have been reported that connect with Siglec-10 and employ the CD24/Siglec-10 interaction as a means of tumor immune evasion." (PMID 37359556, 2023). "High expression of CD24 on tumor cells not only facilitates tumor progression by affecting the proliferation and migration of tumor cells but also allows tumor cells to escape killing by immune cells via interactions with immune cells around the tumor." (PMID 36882399, 2023). "Blocking the binding between CD24 and Siglec-10 or reducing tumor CD24 expression through neutralizing antibodies can restore the ability of macrophages to inhibit tumor cells and improve animal survival." (PMID 37372117, 2023). "Several monoclonal antibodies targeting CD24 have been preclinically investigated in various tumor models." (PMID 37894750, 2023). "To clarify the tumor expression of Cd24 and Cd47 in human GCTs, we performed q-PCR on KGN cell line, which originated from a Stage III granulosa cell carcinoma." (PMID 36823373, 2023). "CD24 expression was high across all molecular subgroups when compared with non-tumor tissues, and it showed significantly higher levels in the SHH and Group 4 than in the WNT subgroup." (PMID 36825029, 2023). "The importance of MDSCs in 4NQO carcinogenesis was confirmed by the study that shows the difference in tumor growth between CD24−/− and CD24+/− mice was blunted by immuno-depletion of MDSCs." (PMID 37373022, 2023). "In combination with EpCAM, we stained tumour specimens for CD24 as a second marker of plastic EMT CSCs, and Vimentin as a mesenchymal marker to identify cells that have undergone EMT." (PMID 37975646, 2023). "In response to a wide range of extracellular stimuli, MAPK cascades are shown to be involved in CD24-induced tumorigenesis in various of tumor cells." (PMID 37919766, 2023). "CD24-Fc treatment also ameliorates the autoimmune response induced by effective tumor vaccination in the heart." (PMID 37346042, 2023). "Some studies showed that the CD24 expression is related to the hypoxia condition in tumor microenvironment." (PMID 37359556, 2023). "We performed mammosphere assay using CD49f+CD24+ tumor cells isolated from Rac1b+/+;MMTV-NIC (or Rac1b+/−;MMTV-NIC) and Rac1b−/−;MMTV-NIC tumors." (PMID 36599922, 2023). "Administration of CD24-Fc with the initial tumor vaccine dampened the therapeutic effect of the vaccine." (PMID 37346042, 2023). "The PD-1/PD-L1 signalling pathway enhances tumor immune escape by inhibiting macrophage normal function and binding Siglec-10 to CD24." (PMID 37958467, 2023). "CSCs, a subpopulation of cells, are characterized by some key markers, such as CD133, CD166, CD44, CD24, SOX2, OCT4, and ALDH, which are associated with tumor initiation, growth, and therapy resistance." (PMID 36827121, 2023).
tumor (continued). "We have shown that immunofluorescent antibody co-staining for EpCAM, Vimentin and CD24 can separate disseminating EMT CSCs from the stromal content of human tumours, a challenge which has confounded previous attempts to develop a predictive EMT signature." (PMID 37975646, 2023). "The functional role of CD24 is either fulfilled by combining with ligands or participating in signal transduction, which mediate the initiation and progression of neoplasms." (PMID 37919766, 2023). "Significant therapeutic survival benefit was observed in vaccine groups either with CD24-Fc or with IgG-Fc when compared with tumor only control groups in both models, but the anti-tumor effect was more profound in the model of delayed CD24-Fc treatment." (PMID 37346042, 2023). "According to report, down-regulation of CD24 inhibits proliferation and induces apoptosis in tumor cells, whereas increases expression of CD24 enhances tumor growth and metastasis." (PMID 37919766, 2023). "After describing the association between CD24 and CD200 expression and tumor progression, we conducted a detailed exploration into the immunosuppressive effects of these molecules." (PMID 37894750, 2023). "The quiescent mesenchymal BCSCs, characterized as CD44+CD24− phenotype, were located at the infiltrating edge of the tumor, whereas epithelial BCSCs, characterized as ALDH+ phenotype, proliferated more actively in a more central area." (PMID 36768876, 2023). "Blocking the expression of CD24 on tumor cells or Siglec-10 on macrophages genetically or via an antibody enhances the phagocytosis of macrophages and suppresses tumor growth in vivo." (PMID 36882399, 2023). "Fourthly, CD24 plays a critical role in promoting tumor immune evasion through its interaction with Siglec-10." (PMID 38313430, 2023). "Through overexpression of CD24, tumor cells interact with Siglec10, which inhibits the activity of macrophages and achieves immune escape." (PMID 37484024, 2023). "Inhibiting the interaction of CD24-Siglec-10 promotes the phagocytosis of CD24 + tumor cells by TAMs, and has been shown to increase survival in preclinical mouse models." (PMID 37919766, 2023). "Knockdown of CD24 or Siglec10, as well as using CD24 monoclonal antibodies to block the interaction of CD24 with Siglec10, significantly enhances macrophage phagocytosis of all CD24-expressing human tumor cells." (PMID 37484024, 2023). "We stained and imaged 59 tumour slides from 54 regions across 50 tumours, stratified on the same criteria as the previous cohort, for EpCAM, Vimentin and CD24." (PMID 37975646, 2023). "Mechanisms of tumorigenesis promotion by CD24 include cancer stem cell regulation, metastasis of tumor cell, proliferation of cancer cells and evasion of immune detection." (PMID 38313430, 2023). "Since then, many groups and many papers support the use of CD24 as a marker for prognosis and predicting clinical outcome in many tumor types." (PMID 38138858, 2023). "CD24-Fc administration with vaccination partially impedes anti-tumor immunity but delaying CD24-Fc administration after initial vaccination reverses this effect." (PMID 37346042, 2023). "Blocking the mutual recognition between CD47-SIRPα or CD24-Siglec10 using large molecular proteins or small molecular drugs represents a promising avenue for tumor immunotherapy." (PMID 37484024, 2023). "“Don’t eat me” axis, e.g., CD47/SIRPα and CD24/Siglec-10 between tumor cells and myeloid cells presents an exciting paradigm for using tumor-induced inhibitory pathways to escape immune surveillance." (PMID 37822933, 2023). "The surface protein CD24, which has been implicated in sorafenib resistance, is overexpressed in HCC tumor tissues and in highly metastatic HCC cell lines." (PMID 36980210, 2023). "CD24-antagonizing antibody SWA11 inhibits tumor growth in vivo in multiple human cancer cell lines, including lung (A549), ovarian (SKOV3ip), pancreatic (BxPC3), and colorectal (HT29) cancer cell lines, in xenograft mouse models." (PMID 37894750, 2023).
tumor (continued). "When CD24 on tumor cells binds to Siglec-10 on different immune cells, it causes immune cell inhibitory signaling cascades mediated by SHP-1/SHP-2, promoting escape from killing by T and NK cells and engulfment by macrophages." (PMID 36882399, 2023). "Our findings indicated that IMM47’s mode of action involves binding to CD24 on the surface of tumor cells, which promotes macrophage activation." (PMID 37846296, 2023). "The effect of the human-specific anti-CD24 mAb ALB9 was investigated by establishing UM-UC-3 human urothelial carcinoma cell tumour models and lung metastasis models." (PMID 38137380, 2023). "CD-Siglec axis: Small-cell lung carcinoma cluster 4 antigen (CD24) expressed on tumor cells interact with sialic acid-binding immunoglobulin-like lectin 10 (Siglec-10) expressed on TAMs." (PMID 38258072, 2023). "Plasma CD24 levels are significantly higher in HCC patients than in controls and are associated with tumor differentiation." (PMID 36980210, 2023). "A relatively small retrospective patient tumor analysis suggests that tumors with a high expression of CD24 show an unfavorable response to cisplatin treatment." (PMID 38138858, 2023). "Published reports strongly suggests that HIF-1α directly binds to the promoter region of CD24 and induces CD24 overexpression which further accelerates tumor formation and metastasis." (PMID 37492478, 2023). "For these tumours, using a variation on the previous image segmentation protocol, the proportion of EpCAM+Vim+CD24+ and EpCAM+Vim+CD24- cells was quantified for each cell in over 9000 imaging fields at the tumour-stroma boundary." (PMID 37975646, 2023). "(A–C) Immunofluorescent four-colour staining of oral tumour specimens for EpCAM (yellow), Vimentin (red) and CD24 (green) with DAPI nuclear stain (blue)." (PMID 37975646, 2023). "We further aimed to evaluate the presence of CD24 protein in the tumor tissue of HNSCC patients of our cohort, in comparison to healthy margin tissues." (PMID 38138858, 2023). "While as a CSCs marker and as a therapeutic target, CD24 remains incompletely understood, the value of targeting it in tumor treatment has been increasingly confirmed." (PMID 37919766, 2023). "Analysing this dataset for EpCAM, Vimentin and CD24 co-expression, we found that 12% of tumour cells (267/2215) were EpCAM+Vim+CD24+." (PMID 37975646, 2023). "This binding event initiates an inhibitory signaling pathway within TAMs through the CD24–Siglec-10 axis, thereby aiding in immune evasion and promoting tumor growth." (PMID 37894750, 2023). "Cancer stemness markers have been reported in cell populations with elevated CD44 and reduced CD24 expression levels that exhibited the same drug-resistant histopathological features of the derived tumor when injected in mice at very low concentrations." (PMID 37169743, 2023). "Although only a small percentage of tumour cells expressed CD24, the CD24-targeted CAR-T was still effective in prolonging survival in mice." (PMID 38137380, 2023). "Immunohistochemistry analysis demonstrated that CD24 was highly expressed in tumor tissue in comparison to healthy surrounding tissue." (PMID 38138858, 2023). "The tumor-seeding potential in immunocompromised (NOD-SCID) mice and DEGs in the tumors were also assessed along with the intra-tumor (CD44+/CD24-) expression using flow cytometry." (PMID 37298091, 2023). "The abundance of CD24+MHC-II+CD11c+ cells in the circulation of tumour-bearing mice treated with the combination therapy was 2.0- and 1.4-fold higher than that in control or IRE monotherapy-treated mice, respectively." (PMID 37433774, 2023). "Remarkably, dAbPD−L1/CD24-mPDA@CuO2 NRs exhibited tumor-targeted CDT triggered by H2O2 and successfully activated immune cells including T cells and macrophages." (PMID 37875918, 2023).
tumor (continued). "Our emphasis was on illustrating how CD24 and CD200 act as signaling checkpoints by engaging their respective receptors, namely, Siglec-10 and CD200 receptor, which are expressed on tumor-associated myeloid cells." (PMID 37894750, 2023). "We found that NDRG1 maintains TGFβ-induced CSCs, specifically ALDH1+ in all cell lines and CD44+/CD24- and side population in primary-tumor-derived cells." (PMID 36594086, 2023). "Examining disseminating tumour cells in over 12,000 imaging fields from 74 human oral tumours, we see a significant enrichment of EpCAM, CD24 and Vimentin co-stained cells disseminating beyond the tumour body in metastatic specimens." (PMID 37975646, 2023). "At the endpoint of inoculation days, the tumors generated from SCARB2 knockout tumor spheroids showed the decreased proportions of CD24, EpCAM, CD13, or CD133 positive cells." (PMID 37739936, 2023). "The day after their second cycle of treatment, tumors were dissected to isolate CD49f+;CD24+ tumor epithelia by FACS and plated in mammosphere culture." (PMID 36599922, 2023). "Experimental investigations involving the deletion of the CD24 gene and therapeutic interventions have shown significant inhibition of tumor growth in animal models and improved patient survival." (PMID 38313430, 2023). "The abundance of CD24+ cells was increased in metastatic peritoneal implants compared to the primary tumor, where it contributed to the attachment of OC cells to fibronectin and collagen of the peritoneal stroma." (PMID 35269636, 2022). "Suggesting that TAMs-mediated increase in CD24– cell clearance is responsible for the reduction in tumor load." (PMID 35938128, 2022). "On the contrary, PPARγ is considered a tumor suppressor that reduces the CD49high/CD24+ mesenchymal stem cells (MSCs) and inhibits tumor angiogenesis of breast cancer." (PMID 36226253, 2022). "In the pathological state of CD24, the organ can capture tumor cells and form distant metastasis by binding to P-selectin on the surface of vascular endothelial cells of distant organs or by interacting with platelets." (PMID 35938128, 2022). "The expression of MUC1 was positively correlated with cancer stem cell markers such as CD24, PSCA and TM4SF1, which indicated that the high expression of MUC1 in malignant cells was associated with tumor proliferation." (PMID 36104333, 2022). "In our previous studies, we identified a high percentage of CD19+CD24+CD38+ Bregs in the tumor microenvironment (TME) and peripheral blood of IBCa patients." (PMID 35935985, 2022). "CD24 is highly expressed in most tumor specimens and is significantly related to the infiltration and proliferation of tumor cells." (PMID 35938128, 2022). "Another strategy was the use of dendritic cells loaded with antibody-coated cancer cells, which targets different surface antigens, including CD24, to cross-present tumor antigens to CD8+ T cells." (PMID 36013184, 2022). "Moreover, CD24+ population is associated with higher tumor stage, nodal metastasis, higher-grade tumors, microscopic lymphatic, venous and neural invasion in PDAC, and reduction in CD24 expression, as observed here, in response to miR-21 KO in PDAC cells may be of significant importance." (PMID 35163198, 2022). "In animal tumor models, interactions of CD24 with P-selectin facilitated contact of tumor cells with the vasculature, and CD24 seems to play an important role for metastases." (PMID 35628262, 2022). "Tumor volume increased in both groups after receiving Tregs, particularly in CD24+MDSC-DCs groups and the difference on tumor volume between the two groups was reduced after receiving Treg reinfusion." (PMID 35707772, 2022). "A higher expression of CD24 in cancerous cells than in other cell clusters has proposed CD24 as a tumor-specific antigen in the mentioned malignancies." (PMID 37551166, 2022).
tumor (continued). "CD24 is suggested as a novel “don't eat me” signal that promotes the tumor immune escape.CD24 is a dominant innate immune checkpoint regarding as a promising immunotherapy target for cancer." (PMID 35585567, 2022). "Siglec-10 on the surface of immune cells can promote the immune escape of tumor cells by binding CD24." (PMID 35418152, 2022). "As such, the conjugate of an anti-CD24 monoclonal antibody with deglycosylated ricin A-chain delayed tumor growth in a small cell lung cancer xenograft model." (PMID 36013184, 2022). "Together, pyrotinib inhibited tumor development by inducing apoptosis and suppressing CD24 expression via the pEGFR/pSTAT3 signaling pathway." (PMID 36231025, 2022). "The protein levels of pAkt and CD44/CD24 in tumor cells were tested with immunohistochemistry analysis." (PMID 35053979, 2022). "MMP1, SDC1, SPP1, and CD24 mRNA declaration was much higher in tumor tissues than in non-tumor tissue." (PMID 35037689, 2022). "CD133 is a CSC marker correlated with poor prognosis in HCC patients, while CD24, another CSC marker, is associated with number and size of tumours and differentiation level of HCC." (PMID 35713728, 2022). "Reversely, CD24 KO in cancer cells also significantly increased the level of cancer cell phagocytosis and reduced tumor outgrowth in vivo, which was taken as support for a role as an immune checkpoint in carcinoma." (PMID 35625912, 2022). "Several studies have shown that high expression of CD24 in tumor cells and its involvement in CRC cell proliferation and invasion is a poor prognostic factor for CRC." (PMID 35938128, 2022). "Anti-CD24 CAR T cell therapy was effective in reducing tumor growth and metastasis in human pancreatic adenocarcinoma xenografts in mice." (PMID 36013184, 2022). "CD24 expression in NSCLC cells has been reported to be associated with disease progression and aggressive tumor behavior." (PMID 36362359, 2022). "Pyrotinib specifically targeted TSC2-deficient cells, inhibited tumor cell viability and induced apoptosis through EGFR-STAT3/CD24 Loop in vivo and in vitro." (PMID 36231025, 2022). "Intriguingly, metastatic tumor growth has been shown to be inhibited when CD24 activity is suppressed." (PMID 36013184, 2022). "Therapeutic inhibition of CD24 using monoclonal antibody leads to macrophage-dependent inhibition of tumor growth in vivo." (PMID 36135216, 2022). "An in vivo xenograft model experiment indicated that CD24-knockout MCF-7 cells had a markedly lower tumor burden than the wild-type group." (PMID 35978372, 2022). "Tumor cells (cluster 0, 2, 5, 6, 7, 8, 10, and 11) were distinguished by the expression of CD24, KRT19, and EPCAM." (PMID 36291687, 2022). "These interactions, including the ones connected to CD24, enable the cells to thrive, migrate out of the BM, and at times develop resistance to anti-tumor therapy." (PMID 35629039, 2022). "Culture of PD-L1 expressing human epithelial breast cancer cells with B cells can induces the development of CD24+CD38+Bregs, which are associated with increased tumour grade and higher frequency of Tregs in patients with invasive breast cancer." (PMID 35350071, 2022). "While it is true, recent advances have revealed multiple molecular mechanism as a prevalent tumor therapy, such as CD24/Siglec-10, EMT, PD-L1/PD-1, C/EBPβ transcription factors and hypoxia/HIF-1α." (PMID 36685947, 2022). "Several malignancies have been found to overexpress sialyated glycans, which connect with Siglec-10 and employ the CD24/Siglec-10 interaction as a means of tumor immune evasion." (PMID 36013184, 2022).